EZR (ezrin)
Diseases named in the same sentence as EZR in open-access papers (continued):
Sharing a sentence is not in itself a finding about the gene and the disease.
esophageal cancer (10 papers, 2015 to 2025). A primary or metastatic malignant neoplasm involving the esophagus. "Survival data showed that high Ezrin expression is associated with poor prognosis in gastric, colorectal and esophageal cancers." (PMID 29190988, 2017). "This study not only shows that PALM2 is upregulated in esophageal cancer and is an independent risk factor for poor prognosis in patients with esophageal cancer but also demonstrates that PALM2 activates ezrin and subsequently promotes the malignant progression of esophageal cancer cells." (PMID 37328063, 2023). "Besides, Ezrin expression was also found to be significantly associated with OS in esophageal cancer." (PMID 29190988, 2017). "Previous studies show that ezrin promotes the development of esophageal cancer by regulating the rearrangement of the cell cytoskeleton." (PMID 37328063, 2023). "Prenylated PALM2 interacts with ezrin at the K253/254/262/263 lysine residues in the ezrin FERM domain to activate ezrin and promote the migration of esophageal cancer cells." (PMID 37328063, 2023). "In the present study, we performed a meta-analysis to explore the possible role of Ezrin expression in the progression and prognosis of gastric, colorectal and esophageal cancers." (PMID 29190988, 2017). "Respectively, 4/1/4/1 studies were examined for any association between Ezrin expression and tumor grade/TNM stage/lymph node involvement/distant metastasis in esophageal cancer." (PMID 29190988, 2017). "By conducting a literature review, we found that Ezrin is significantly up-regulated in various tumors, including esophageal cancer, but the specific pathways and mechanisms involved remain unclear." (PMID 37791063, 2023). "•Prenylated PALM2 activates ezrin to promote the migration of esophageal cancer cells." (PMID 37328063, 2023). "Moreover, there was a significant correlation between Ezrin and yes-associated protein/connective tissue growth factor (YAP1/CTGF) levels in esophageal cancer." (PMID 37791063, 2023). "Furthermore, high Ezrin expression is associated with poor prognosis according to the pooled data of OS and DFS in gastric/colorectal/esophageal cancers." (PMID 29190988, 2017). "In total, 5 studies provided data on Ezrin expression and esophageal cancer." (PMID 29190988, 2017). "Significant association was also observed between high Ezrin expression and OS in esophageal cancer (HR = 1.49, 95% CI = 1.17–1.89, P = 0.001), with no significant heterogeneity noted (I2 = 0.0%, P = 0.914)." (PMID 29190988, 2017). "Thus, Ezrin likely plays an important role in esophageal cancer occurrence and development." (PMID 37791063, 2023). "Moreover, our results reveal that autoantibody against Ezrin combined with other specific autoantibodies in esophageal cancer may shed light on a promising way to develop a highly sensitive test for early diagnosis of ESCC in the future." (PMID 28298808, 2017). "Bioinformatics analysis confirmed that Ezrin is highly expressed in ESCC, and we identified a significant difference in Ezrin expression among esophageal cancer at different clinical stages." (PMID 37791063, 2023). "Ezrin and YAP1/CTGF expression levels in esophageal cancer tissue were analyzed by immunohistochemistry." (PMID 37791063, 2023). "Moreover, analysis of data from the GEPIA database revealed a significant correlation between Ezrin and YAP1 levels in esophageal cancer tissue (P = 0.0024; R = 0.1)." (PMID 37791063, 2023). "Besides, molecules, like Caveolin-1, Ezrin, and LAMP3, were also checked in esophageal carcinoma tissues." (PMID 34178655, 2021). "In a recent meta‐analysis 42, the results showed that ezrin expression was not correlated with the distant metastasis of either gastric or esophageal cancers." (PMID 31376222, 2019). "Only one study reported on Ezrin expression and TNM stage/distant metastasis in esophageal cancer." (PMID 29190988, 2017).
metastatic disease (10 papers, 2011 to 2023). "As ezrin plays a critical role in cancer cell invasion, we next explored its prognostic potential in patients with higher risk of metastatic disease." (PMID 30678714, 2019). "It has been demonstrated that Ezrin expression is higher in invasive or metastatic tumors, and Ezrin expression is necessary for the invasive ability of cervical tumor cells through induction of epithelial-mesenchymal transition (EMT)." (PMID 29587669, 2018). "Expression of miR-96 and Ezrin was also examined in primary RCC samples from 17 patients with metastatic disease and 46 patients who maintained remission during a follow-up period of 37 months." (PMID 26419932, 2015). "We have observed that, besides being 100% ezrin positive, those patients with synovial histology had most often locally advanced disease (with a better prognosis than metastatic disease), and we believe that this clearly confounds this data." (PMID 21785570, 2011). "Here, we review the roles of Ezrin and its interacting proteins that ultimately allow it to be a key player in metastasis and aim to increase our understanding of how Ezrin contributes to metastatic disease and its potential as a therapeutic target." (PMID 37371090, 2023). "Ezrin has been widely studied as a possible therapeutic target for treating metastatic disease." (PMID 37371090, 2023). "The proportion of patients with metastatic disease was equal in the positive and negative ezrin expression groups." (PMID 28246524, 2017).
sarcoma (9 papers, 2008 to 2025). A usually aggressive malignant neoplasm of the soft tissue or bone. "Given the published association between ezrin expression and inferior outcomes in other sarcomas, our finding was unanticipated." (PMID 28246524, 2017). "The results suggested that ezrin expression is significantly increased in cancers of mesenchymal origin (sarcomas)." (PMID 31376222, 2019). "In addition, as neratinib blocks both ERBB2 and Ezrin phosphorylation, this drug may have particular utility in sarcomas." (PMID 31380285, 2019). "Further study is needed to investigate whether the cutoff value could impact the prognostic value of ezrin for sarcomas, which remained vague due to the limited number of studies included and the lack of uniformity in terms of what was considered ezrin positive in the present analysis." (PMID 31376222, 2019).
cystic fibrosis (7 papers, 2015 to 2025). Autosomal recessive disorder caused by pathogenic variants in the CFTR gene (cystic fibrosis transmembrane conductance regulator), which encodes a chloride and bicarbonate channel expressed in epithelial cells, and follow the diagnosis criteria. "We previously reported that the level of ezrin is reduced in the MΦs of individuals with cystic fibrosis, a disease characterized by lung hyperinflammation, and chronic infection initiated by airway dehydration and compromised mucociliary clearance." (PMID 39613751, 2024). "Future studies should investigate the role of ezrin in the context of chronic lung inflammatory models, such as cystic fibrosis and pulmonary fibrosis, since our finding on the profound impact of loss of ezrin on IMs and TGF-β signaling pathway." (PMID 39613751, 2024). "NHERF1 is an important regulator of different proteins, trafficking and localized as a cystic fibrosis transmembrane conductance regulator, ezrin and β-catenin." (PMID 31336689, 2019). "This is supported by two observations: first, it has previously been reported that a multiprotein complex (NHERF1-CFTR-ezrin-actin) plays a significant role in maintaining tight junction organization and function in cystic fibrosis epithelial cells." (PMID 26594334, 2015). "Phosphorylated ezrin restores moreover actin organization and PKA submembrane compartmentalization in cystic fibrosis airway cells, which corrects the chloride secretion defect observed in the presence of the trafficking-incompetent F508del mutant of the cystic fibrosis transmembrane regulator." (PMID 29765373, 2018). "Furthermore, RhoA, Ezrin, NHERF1, and actin form multiprotein complexes that are involved in reorganizing the actin skeleton network, thereby regulating the integrity and function of airway epithelia in cystic fibrosis." (PMID 39668431, 2025).
lung adenocarcinoma (7 papers, 2013 to 2025). A carcinoma that arises from the lung and is characterized by the presence of malignant glandular epithelial cells. "In lung adenocarcinoma, tumor-associated macrophages promote ezrin-phosphorylation-mediated epithelial-mesenchymal transition through fucosyltransferase IV-induced fucosylation, in which upregulation of phospho-Smad3 plays a pivotal role." (PMID 33046439, 2021). "Together, our results revealed that TAMs promote Ezrin phosphorylation-mediated EMT in lung adenocarcinoma through FUT4/LeY- mediated fucosylation." (PMID 28423676, 2017). "We demonstrated that TAMs promote Ezrin phosphorylation-mediated EMT in lung adenocarcinoma through FUT4/LeY- mediated fucosylation." (PMID 28423676, 2017). "has-miR-183 mainly functions to regulate lung adenocarcinoma metastasis by regulating the expression of Ezrin and other metastasis-related genes." (PMID 23593434, 2013). "Our in vivo experiments confirmed that M2 macrophages could significantly up-regulate the expression of Vimentin, LeY and p-Ezrin and down-regulate the expression of E-cadherin, thus promote the growth and EMT of lung adenocarcinoma xenograft." (PMID 28423676, 2017).
soft tissue sarcoma (7 papers, 2011 to 2020). A malignant neoplasm arising from muscle tissue, adipose tissue, blood vessels, fibrous tissue, or other supportive tissues excluding the bones. "The results showed that positive/high ezrin expression was significantly associated with poor prognosis in patients with bone and soft tissue sarcomas, which was consistent with the results of previous analyses in patients with solid cancers." (PMID 31376222, 2019). "In the present study, 19 studies with a total of 1316 bone and soft tissue sarcoma patients were included to evaluate the clinicopathological and prognostic value of ezrin expression." (PMID 31376222, 2019). "However, the clinical prognostic significance of ezrin in patients with bone and soft tissue sarcomas remains inconclusive." (PMID 31376222, 2019). "Previously, a meta‐analysis was conducted to evaluate the prognostic value of high ezrin expression in patients with solid tumors, including bone and soft tissue sarcomas 20; however, the number of included studies was limited (n = 9), and therefore, the results were inconclusive." (PMID 31376222, 2019). "In the present meta‐analysis, the correlations between ezrin expression and prognostic and clinicopathological outcomes (CP) were evaluated to investigate whether ezrin expression could serve as a prognostic and clinicopathological biomarker for patients with bone and soft tissue sarcomas." (PMID 31376222, 2019). "However, the clinical prognostic significance of ezrin in patients with bone and soft tissue sarcomas remains unclear." (PMID 31376222, 2019). "However, the prognostic and clinicopathological significance of ezrin in patients with bone and soft tissue sarcomas remains unclear." (PMID 31376222, 2019). "Our findings indicated that ezrin overexpression was significantly correlated with poor survival and more advanced tumor progression in bone and soft tissue sarcomas, which suggests that ezrin might be a valuable prognostic biomarker and a potential therapeutic target." (PMID 31376222, 2019). "The role of Ezrin, a cytoskeleton linker protein that is actively involved in regulating the growth and metastatic capacity of cancer cells, has been reported in adult soft tissue sarcoma with a direct correlation between IHC staining intensity, histological grade and infiltrative growth pattern." (PMID 25613038, 2015). "As chemo/radiotherapy was of great importance to patient prognosis, a stratified analysis of the effect of prechemotherapy/radiotherapy on OS was conducted, and the results showed that the prognostic value of ezrin expression in patients with bone and soft tissue sarcomas was not altered." (PMID 31376222, 2019).
colon adenocarcinoma (6 papers, 2021 to 2024). "Radixin, moesin, and ezrin were preferentially distributed on the plasma membrane in human colon adenocarcinoma cells, However, the mRNA levels of ezrin and moesin were observed to be higher than those of radixin." (PMID 39457653, 2024). "Other researchers have reported that human colon adenocarcinoma sublines (EB3, 3LNLN, and 5W) shows higher protein expression levels of ezrin in the whole cellular extracts with higher migratory and adhesive abilities in comparison with their parental LS180 cells." (PMID 34577564, 2021). "Moreover, the gene correlation analysis revealed a positive correlation of PD-L1 with ezrin and moesin but not radixin in the clinical human colon adenocarcinoma samples from the TGCA database." (PMID 34577564, 2021).
Ewing sarcoma (6 papers, 2010 to 2025). A small round cell tumor that lacks morphologic, immunohistochemical, and electron microscopic evidence of neuroectodermal differentiation. "Ezrin is closely associated to p85 subunit, which activates the PI3K/Akt pathway and plays an important role in modulating Ewing's sarcoma cell survival, invasion, and metastasis." (PMID 32047564, 2020). "The aim of our study was to describe the patterns and frequency of ezrin expression and correlate this with clinical characteristics and outcomes in patients with Ewing sarcoma." (PMID 28246524, 2017). "The relationship between ezrin expression and outcome was analyzed in a cohort of 53 newly diagnosed Ewing sarcoma patients treated between 2000 and 2011." (PMID 28246524, 2017). "Ezrin was expressed in 38/53 (72%) of the Ewing sarcoma samples in our study." (PMID 28246524, 2017). "Previous work in Ewing sarcoma (EWS) cell lines revealed ubiquitous, high level ezrin expression and demonstrated that the action of ezrin is dependent on the AKT/mTOR pathway." (PMID 28246524, 2017). "In our cohort of Ewing sarcoma patients, positive ezrin expression was not correlated with a worse EFS, OS, or increased incidence of metastasis at diagnosis." (PMID 28246524, 2017). "Moreover, ezrin promotes growth and survival via AKT/mTOR pathway activation in Ewing's sarcoma cell lines." (PMID 19680458, 2010).
liver cancer (6 papers, 2007 to 2020). An epithelial or non-epithelial malignant neoplasm that arises from the liver. "Here we show that ROCK2 is a novel target of celastrol and inhibition of ROCK2 suppresses elicited ezrin activation and liver cancer cell migration." (PMID 32647287, 2020). "Mechanistically, celastrol inhibits the ROCK2-mediated phosphorylation of ezrin at Thr567 which harnesses liver cancer cell migration." (PMID 32647287, 2020). "According to our previous studies, ROCK hyper-phosphorylating on ezrin is related to liver cancer metastasis." (PMID 32647287, 2020). "We show that ROCK2 is a novel target of celastrol and inhibition of ROCK2 suppresses elicited ezrin activation and liver cancer cell migration." (PMID 32647287, 2020). "The similar expression trend of the genes Pyk2 and FAK with ezrin and fibronectin might also suggest the potential role of Pyk2 in liver cancer metastasis/recurrence." (PMID 17551499, 2007). "Our data demonstrated that EZR, CLIC5 and PODXL co-localization in the liver only occurs under the studied pathological conditions, suggesting that these proteins are potential biomarkers of liver cancer." (PMID 26135398, 2015).
lymphoma (6 papers, 2010 to 2022). A malignant (clonal) proliferation of B- lymphocytes or T- lymphocytes which involves the lymph nodes, bone marrow and/or extranodal sites. "Our findings are in agreement with data obtained for a constitutively polarized murine lymphoma cell line, where transfection with T567D ezrin increased uropod size, whereas 1–310 ezrin reduced the fraction of cells with uropod." (PMID 23579783, 2013). "In addition phosphorylated ezrin has been reported to interact with Dbl and activate Rho in T-lymphoma cells." (PMID 20939895, 2010). "The down-regulated CAPZA1, CAPZB, EFHD2, EZR and PCMT1 proteins are involved in cell–cell adhesion; their reduced levels are compatible with the metastatic behavior of lymphoma cells." (PMID 36291816, 2022). "In studies with a murine T lymphoma cell line and with naïve human T cells, overexpression of the phosphomimetic, constitutively active mutant ezrin T567D [but not of wild type (WT) ezrin] has been reported to increase the size of the uropod and enhance chemokine-induced chemotaxis." (PMID 23579783, 2013).
tongue SCC (6 papers, 2013 to 2023). "The results of the present study suggest that ezrin, ERK, STAT 3, and AKT are involved in the development from tongue CIS to tongue SCC, that AKT is associated with T stage, and that ERK is associated with alcohol and smoking habits." (PMID 32281236, 2020). "Recently, one group reported the regulating relationship between miR-211-5p and EZRIN in tongue squamous cell carcinoma." (PMID 31333725, 2019). "In contrast, tongue SCC samples demonstrated membranous and cytoplasmic ezrin staining, and the cytoplasmic staining was greater in these samples than in the normal tongue mucosa samples." (PMID 23357878, 2013). "This study aimed to clarify the roles of ezrin in tongue SCC progression with ezrin RNA interference (RNAi) in a cell line derived from tongue SCC." (PMID 23357878, 2013). "The researchers found that miR-211-5p could bind to the 3′-UTR of EZRIN mRNA and miR-211-5p upregulation significantly impaired tongue squamous cell carcinoma proliferation and resumed the chemo-sensitivity." (PMID 31333725, 2019). "Furthermore, Ezrin was found to be involved in cancer proliferation by affecting cell cycle distribution, as silencing of Ezrin decreased the S and G2/M fractions and the growth rate in human tongue SCC cell line HSC-3." (PMID 26202611, 2015). "Our results suggest that ezrin plays an important role in the invasive growth of tongue SCCs." (PMID 23357878, 2013). "Ezrin is often overexpressed in primary tongue SCCs and may have an important role in their growth, migration, and invasiveness possibly via its relationship with the E-cadherin/β-catenin complex and the cadherin switch." (PMID 23357878, 2013). "Ezrin was often overexpressed in primary tongue SCCs; thus, it may also play an important in vivo role in the malignant behavior of tongue SCCs." (PMID 23357878, 2013). "We performed immunohistochemical staining of ezrin, ERK, STAT3, and AKT in tumors from patients with tongue carcinoma in situ (CIS, n = 17) and tongue squamous cell carcinoma (SCC, n = 46)." (PMID 32281236, 2020). "We used human tongue SCC and noncancerous tissue microarrays to immunohistochemically analyze the ezrin expression level and its relationship with proliferative activity." (PMID 23357878, 2013). "Unlike AKAP12, Ezrin expression and increased malignancy seem to correlate in various human cancers, including uterine cervical cancer, uveal malignant melanoma, tongue SCC, hepatocellular carcinoma, brain astrocytoma, and atypical endometrial hyperplasia and uterine endometrioid adenocarcinoma." (PMID 26202611, 2015). "In tongue squamous cell carcinoma (SCC), high Ezrin expression correlated with an increased Ki-67 index, a marker for tumor proliferation and aggressiveness, although no obvious connection between the expression level of Ezrin and the tumor stage was observed in this study." (PMID 26202611, 2015).